RNU6ATAC21P (RNA, U6atac small nuclear 21, pseudogene)
Gene: Small nuclear RNA gene on chromosome 6 (10,222,036 to 10,222,161, forward strand). Ensembl gene ENSG00000221583.
Homologues: Orthologues: chimpanzee RNU6ATAC21P (100% identical). Paralogues in human: RNU6ATAC (88% identical), RNU6ATAC41P (85% identical), RNU6ATAC8P (85% identical), RNU6ATAC7P (83% identical), RNU6ATAC6P (83% identical), RNU6ATAC27P (80% identical), RNU6ATAC19P (63% identical), RNU6ATAC39P (55% identical), RNU6ATAC22P (54% identical).